PF4 (platelet factor 4)
Diseases named in the same sentence as PF4 in open-access papers (continued):
Sharing a sentence is not in itself a finding about the gene and the disease.
Thrombocytopenia (continued). "In HIT, anti-PF4/heparin (PF4/H) antibodies activate platelets upon binding with FcγRIIA receptors, thereby triggering the secretion of granules and production of membrane microparticles, ultimately resulting in thrombocytopenia." (PMID 35008518, 2021). "Immunoassays can be used to evaluate the binding of HIT antibodies to PF4/heparin (or PF4/polyanion) complexes, which may result in immune thrombosis and thrombocytopenia." (PMID 34526009, 2021). "Anti-PF4 antibodies are key biomarkers of heparin-induced thrombocytopenia." (PMID 34029337, 2021). "Furthermore, strong antibody responses against PF4-polyanion were demonstrated and the intravascular coagulation resembled autoimmune heparin-induced thrombocytopenia." (PMID 34356644, 2021). "This, coupled with the opsonisation of the Ab-vaccine component-PF4 complexes by complement components, could then mediate the removal of platelets by mononuclear phagocytes, resulting in thrombocytopenia." (PMID 34557868, 2021). "This B cell tolerance could be disturbed after exposure to heparin and also in some inflammatory conditions, where anti-PF4 IgG antibodies elicit thrombus formation and thrombocytopenia via multiple mechanisms." (PMID 34443589, 2021). "It has been demonstrated that PF4 bound to various bacteria, induces the generation of antibodies that could cross-react with the major antigen in PF4/heparin complex, resulting in heparin-induced thrombocytopenia." (PMID 32849656, 2020). "We describe a rare case of autoimmune heparin-induced thrombocytopenia after transcatheter aortic valve implantation in which antibodies against platelet factor 4/heparin have led to platelet activation even after heparin cessation, causing a delayed drop in platelet count to below 20 × 10 9 /L." (PMID 31263800, 2019). "Besides the mechanism of platelet-factor 4/heparin complexes in heparin-induced thrombocytopenia, it is likely that heparin potentiates platelet activation via binding to αIIbβ3 leading to thrombocytopenia." (PMID 30978226, 2019). "However, what triggered the thrombocytopenia was attributed to IgG antibodies to heparin‐PF4 complex." (PMID 29701015, 2018). "Clinical reports have indicated pentosan polysulfate can induce thrombocytopenia and thrombosis at least to the same degree as heparin, and in vitro studies have shown that polyphosphates form antigenic complexes with PF4 which are recognized by anti-PF4 antibodies." (PMID 28974047, 2017). "Platelet factor 4 as heparin antidote did not complete clinical trial, probably due to safety reasons (it increases the risk of heparin-induced thrombocytopenia)." (PMID 25781030, 2015). "These patients develop a consumptive thrombocytopenia from cardiopulmonary bypass required during LVAD implantation which also has been shown to release platelet factor 4 which could lead to false positivity with ELISA testing." (PMID 24656312, 2014). "Finally, Runx1F/F/Pf4-Cre mice suffer from low platelet counts in peripheral blood (thrombocytopenia), consistent with abnormal megakaryocytic maturation." (PMID 23717578, 2013). "The presence of PF4 also determines whether HIT antibodies will lead to thrombocytopenia and/or thrombosis because only immune complexes of antibody plus target antigen, not antibodies alone, mediate the pathogenic platelet activation." (PMID 23561460, 2013). "However, the composite determination of the anti-PF4/heparin antibody and thrombocytopenia, as well as the administration of antiplatelet drugs, was not predictive for the risk of thromboembolic events in the maintenance hemodialysis patients." (PMID 23646121, 2013). "Related to HIT it has been reported that the induction of anti-PF4 autoantibodies and platelet activation in a subset of patients may result in the observed combination of thrombocytopenia and thromboses mainly in large vessels including cerebral venous sinus (left side)." (PMID 35084333, 2022).
Thrombocytopenia (continued). "Indeed, PF4 was shown to play a critical role in heparin-induced thrombocytopenia." (PMID 34029337, 2021). "These auto-anti-PF4 antibodies falsely induce positivity of anti-PF4/H ELISA detection, but functional tests are negative, which could represent a problem for managing these patients when investigating the causes of thrombocytopenia." (PMID 35008518, 2021). "Furthermore, UFH might stimulate the development of antibodies against heparin-platelet factor 4 complexes, which induce heparin-thrombocytopenia and thrombosis (HITT)." (PMID 34436380, 2021). "Specifically, the deposition by activated platelets of the chemokine platelet factor 4 at sites of inflammation promotes adhesion of neutrophils on endothelial cells and thrombogenesis, and it seems deeply involved in the phenomenon of vaccine-induced thrombocytopenia and thrombosis." (PMID 34948438, 2021). "Interestingly, in several patients, unusual thrombosis and thrombocytopenia may be associated with the presence of anti-PF4 antibodies, even in the absence of prior heparin therapy." (PMID 41601650, 2026). "PF4 is a key antigen in heparin-induced thrombocytopenia (HIT), which shares similar clinical manifestations with APS, such as thrombocytopenia and thrombosis." (PMID 41601650, 2026). "Thrombocytopenia and thrombosis following heparin exposure (HIT) have been recognised for more than 50 years and are known to be due to anti‐PF4 antibodies." (PMID 40289696, 2025). "Our study demonstrates that BET inhibition induces thrombocytopenia in vivo by altering GATA1 gene expression and its downstream genes, NFE2 and PF4, which regulate megakaryopoiesis and thrombopoiesis." (PMID 40937321, 2025). "Platelet factor 4 (PF4)-related thrombotic/antibody disease is particularly rare in pediatrics; while immune heparin-induced thrombocytopenia is generally described in adult patients, it can occur in younger patients." (PMID 39759125, 2025). "Parallels in the clinical presentation between CM and other anti-PF4 disorders, such as HIT and VITT, include severe thrombocytopenia, endothelial dysfunction, evidence of consumptive coagulopathy, and microvascular thrombosis." (PMID 38652559, 2024). "A key precursor for HIT is the formation of PF4/heparin immune complexes that are ultimately recognized by so called “HIT” antibodies, leading to persistent low platelet count (thrombocytopenia) and/or thromboembolic complications (thrombosis)." (PMID 38798628, 2024). "Anti-PF4 antibodies might not be the only cause for thrombocytopenia in VITT." (PMID 37834770, 2023). "In the control morphology, due to persistent anemia and thrombocytopenia, HIT was suspected; therefore, anti-PF4/H Abs were marked, with a positive result." (PMID 37834820, 2023). "This new event occurs as an atypical thrombosis associated with thrombocytopenia, including CVST, from 5 to 15 days after the vaccination, and it might be mediated by the cross-reactivity between antibodies generated after vaccination and platelet factor 4 (PF4)." (PMID 37896978, 2023). "Our patients showed thrombocytopenia, high D-dimer levels, and positive HIT screens or anti-PF4 antibodies in the majority of cases." (PMID 37182082, 2023). "After the implementation of treatment, progressive thrombocytopenia raised the suspicion of HIT, which was confirmed by a positive result for the presence of anti-PF4/H Abs." (PMID 37834820, 2023). "The first few cases of vaccine-induced thrombocytopenia and prothrombotic syndrome (VITT) were reported with the AstraZeneca vaccine, where pathological antibodies against platelet factor 4 (PF4) were found." (PMID 35326363, 2022). "Due to the occurrence of thrombocytopenia with extensive venous thrombosis, VITT was suspected, and an ELISA test for anti-platelet factor 4 (PF4) antibody was performed using the Lifecodes® PF4 IgG ELISA assay (Immucor, GTI Diagnostics, Waukesha, WI, USA." (PMID 36560433, 2022).
Thrombocytopenia (continued). "In consideration of the presence of progressive thrombosis, thrombocytopenia, and symptoms similar to heparin-induced thrombocytopenia (HIT), these researchers determined the existence of antibodies to platelet factor 4 (PF4)." (PMID 35884946, 2022). "Of note, vaccination with ChAdOx1-S/ChAdOx1 nCoV-19 is associated with an increased risk for other antibody-related diseases, such as Guillain–Barre syndrome and platelet factor 4 (PF4) antibody-related vaccine-induced thrombosis and thrombocytopenia (VITT)." (PMID 35737110, 2022). "T4-noTS would mean that platelets, activated by low concentrations of anti-PF4 antibodies, aggregate mainly at sites where predisposing factors (e.g., pro-inflammatory environment, blood stasis) are present without causing massive consumption of platelets and thrombocytopenia." (PMID 36247442, 2022). "As an immunologic condition, HIT is induced by IgG antibodies recognizing complexes of platelet factor 4 (PF4) and heparin and presents with thrombocytopenia and thrombosis." (PMID 35922765, 2022). "In the majority of cases, previously healthy patients presented with thrombocytopenia, elevated D-dimer and low fibrinogen levels, and often high concentrations of the anti-PF4 (platelet factor 4) antibodies." (PMID 36142094, 2022). "Among patients with VTE and thrombocytopenia after vaccination for SARS-CoV-2, PF-4 antibodies were tested in five patients with VTE after adenovirus-based vaccination and were positive in five patients." (PMID 35215771, 2022). "We also found that PF4 levels were lower in type 2B compared to type 1 VWD, especially in those with persistent thrombocytopenia." (PMID 36165954, 2022). "Thrombocytopenia is likely to be due to direct binding and activation of platelets by VITT antibody/PF4 complexes." (PMID 36064843, 2022). "In a report including 28 patients after receiving AZD122 with thromboembolic events, all of them were tested positive for anti-platelet factor 4(PF4)-heparin antibodies, which clinically mimics auto-immune heparin-induced thrombocytopenia." (PMID 33923054, 2021). "We generated platelet-specific ADAP knockout mice (ADAPfl/fl PF4-Cretg) and reported recently that these mice resemble the phenotype of conventional ADAP knockout mice showing thrombocytopenia and augmented re-bleeding from tail wounds." (PMID 31632410, 2019). "Over the next few days, thrombocytopenia was noted, the heparin drip was stopped, and HIT antibodies (antibodies targeting the complex of platelet factor 4 and heparin; PF4-H AB) and serotonin release assay (SRA) tests were sent." (PMID 30729049, 2019). "The shift could potentially be explained by the severe and chronic thrombocytopenia suffered by Gata1cKOMK mice; still we could not discard Gata1-dependent or -independent alterations in relevant factors such as Pf4 or TPO to be causative of the misbalance observed at the progenitor level." (PMID 27152938, 2016). "All 100 patients with thrombocytopenia and recent heparin exposure underwent PIFA and Gen-Probe PF4 testing." (PMID 23876263, 2013). "Furthermore, we demonstrated that seroconversion of the IgG-class anti-PF4/heparin antibody could be an independent risk factor of symptomatic DVT in the absence of thrombocytopenia." (PMID 21261941, 2011). "The typical time window, which is already known from HIT and VITT, of at least 4 to 5 days between the triggering agent and onset of thrombocytopenia or thrombosis is also present in VITT-like disorders and reflects the time that is needed to produce relevant titers of anti-PF4 antibodies." (PMID 40236285, 2025). "Examples are a 35-year-old woman with CVST, thrombocytopenia, high D-dimer levels, and anti-PF4 antibodies with a strongly positive PF4-dependent but negative heparin-dependent platelet activation test who died from a fatal secondary intracerebral bleeding." (PMID 40573981, 2025).
Thrombocytopenia (continued). "For all disorders with anti-PF4 antibodies, timely identification in patients with thrombocytopenia with or without thrombosis is crucial for successful therapy." (PMID 40236285, 2025). "The combination of severe thrombocytopenia and thrombosis raised suspicion for anti-PF4-mediated immunothrombosis without proximate heparin exposure, given the absence of prior heparin treatment." (PMID 40276517, 2025). "This was based on thrombocytopenia, multiple thrombotic events, macrophage activation syndrome, and positive anti-PF4 antibodies despite no prior exposure to heparin." (PMID 41427155, 2025). "HS37 does not bind to platelet factor 4 and thus has diminished ability to induce, another side effect of heparin, heparin-induced thrombocytopenia." (PMID 40512794, 2025). "Without adequate GATA1 activity, PF4 expression is reduced, leading to impaired megakaryocyte development and subsequent thrombocytopenia." (PMID 40937321, 2025). "Type 2 heparin-induced thrombocytopenia (HIT) is an immune-mediated, prothrombotic disorder driven by IgG antibodies against platelet factor 4 (PF4)/heparin complexes, leading to thrombocytopenia and platelet activation via FcγRIIa receptors, resulting in a hypercoagulable state." (PMID 41450710, 2025). "We therefore advocate the British Society of Haematology (BSH) Expert Haematology Panel recommendations to test for anti‐PF4 antibodies in patients with thrombocytopenia, thrombosis and a D‐dimer of >4000 ng/mL regardless of vaccine exposure." (PMID 40298004, 2025). "Anti-PF4/H testing is crucial only in cases where thrombotic PF4-related disorders are suspected, such as HIT (using a probability score) or VITT (with thrombosis and thrombocytopenia), following ISTH guidelines." (PMID 40123654, 2025). "Although CXCL7 and PF4 may initially rise in response to bacterial invasion, their levels significantly decrease as DIC and sepsis-related thrombocytopenia progress, indicating worsening immune and coagulation dysfunction." (PMID 40864331, 2025). "Neither PMA nor sP-sel correlated with the levels of anti-PF4/H in the absence of thrombocytopenia or true clinical suspicion of HIT or VITT." (PMID 40123654, 2025). "In both reported patients, the MGUS antibodies were produced from a single clone of anti-PF4 plasma cells, and resulted in recurrent thrombosis and thrombocytopenia despite them having no previous exposure to heparin." (PMID 38398325, 2024). "One patient with a positive EIA (Case #3) experienced an increase in anti-PF4 OD post vaccination without developing thrombocytopenia." (PMID 39336949, 2024). "They suggest a three-hit hypothesis where SP activates endothelium, thereby recruiting and activating platelets, and platelets reactively release PF4 which complexes with some neoantigen that augments VITT thrombi and thrombocytopenia." (PMID 37261122, 2023). "Following vaccination, some participants with anti-PF4/polyanionic antibodies had elevated D-dimer levels, while only one developed thrombocytopenia and no thrombotic events were observed." (PMID 37674185, 2023). "Laboratory findings included mild to severe thrombocytopenia and the occurrence of anti-platelet factor 4 (aPF-4) antibodies in the absence of heparin exposure." (PMID 36741657, 2023). "Our patient did not have thrombocytopenia at the presentation, and we did not have the ELISA anti-PF4 antibodies test available, so we established the diagnosis of Probable VITT (according to the Expert Hematology Panel)." (PMID 36423045, 2022). "PF4 and VWF may also form complexes; recognition of PF4-VWF complexes by heparin-induced thrombocytopenia antibodies contributes to thrombus propagation." (PMID 36131342, 2022). "No thrombocytopenia or antibodies against platelet factor 4 (PF4) were observed after additional booster vaccination." (PMID 36097029, 2022).
Thrombocytopenia (continued). "In one study, four of eight VITT patients (50%) with thrombocytopenia but without thrombosis also tested strongly positive for anti-PF4, platelet-activating antibodies." (PMID 36352844, 2022). "This condition can be similar to heparin-induced thrombocytopenia (HIT), as both are related to the presence of antibodies against platelet factor 4 (PF4), with thrombocytopenia and consequent thrombosis, although the antigenic target seems to be different in the two situations." (PMID 35892907, 2022). "Most patients with thrombocytopenia and thrombotic events showed that increased levels of PF4 and anti-PF4 antibodies are found in patients with COVID-19 despite no history of heparin use." (PMID 35159235, 2022). "The presented patient fulfilled the criteria for probable VITT (highly elevated D-dimers, timing of the symptoms related to vaccination, CVST and thrombocytopenia, and no assessment of anti-PF4 antibodies)." (PMID 35207456, 2022). "This thrombocytopenia is not mediated by “heparin-induced thrombocytopenia” but via generating platelet-activating antibodies against platelet-factor 4 (PF4), designated as “vaccine-induced immune thrombotic thrombocytopenia (VITT)”." (PMID 34835248, 2021). "Moreover, the same group showed in vivo that IdeS prevented thrombocytopenia and thrombin activation (i.e., HIT) when 5B9 and UFH were administered to transgenic mice expressing human FcγRIIa and PF4." (PMID 33578859, 2021). "Binding of CXCL4(PF4) to heparin is well established as a mechanism for inducing autoantibodies to CXCL4(PF4)/heparin in HIT2 and has been proposed as a mechanism by which SARS‐CoV‐2 infection might induce thrombocytopaenia." (PMID 34691454, 2021). "In cases of thrombocytopenia and/or evidence of thrombosis, a test for heparin-induced thrombocytopenia (HIT-ELISA) should be performed, which is based on the immunological detection of antibodies against the complex of platelet factor 4 (PF4) and heparin." (PMID 34202817, 2021). "There is no proof that thrombocytopenia is the result of platelet destruction due to anti-PF4 antibodies or anti-PL antibodies." (PMID 34833382, 2021). "If the PF4-ELISA produces a negative result and if there is no thrombocytopenia, then TTS is ruled out." (PMID 34443589, 2021). "Even though the degree of thrombocytopenia and platelet activation were similar between dengue-infected and HIV plus dengue-coinfected patients, plasma levels of the platelet-derived chemokines RANTES/CCL5 and PF4/CXCL4 were lower in coinfection." (PMID 31068600, 2019). "In contrast, anticoagulant mimetics can be designed to bind antithrombin III but not PF4, thereby removing drug induced thrombocytopenia as a potential side-effect (see this review)." (PMID 28974047, 2017). "In the second case, an elderly patient developed the piperacilin-dependent platelet antibodies and nonpathogenic heparin/PF4 IgA antibodies, which led to the drug-induced thrombocytopenia after pneumonia treatment with piperacilin/tazobactam." (PMID 29180919, 2017). "It follows that reduction of serum PF4 content in newly diagnosed AML is not due to thrombocytopenia." (PMID 23915341, 2013). "Antibodies directed against platelet factor 4 (PF4) are at the origin of two major clinical entities that are distinct but have strong clinical and biological similarities: heparin-induced thrombocytopenia (HIT) and vaccine-induced immune thrombosis and thrombocytopenia (VITT)." (PMID 41302191, 2025). "In contrast to the transient character of virus-triggered or passively transmitted anti-PF4 disorders, there is an only recently recognized patient group in whom VITT-like antibodies have persisted over years and have triggered chronic recurrent thrombosis with thrombocytopenia [59,63,]." (PMID 40236285, 2025). "PF4/heparin complexes can interact with endothelial cells and monocytes, leading to tissue factor expression and enhanced thrombin generation, thereby driving thrombosis rather than isolated thrombocytopenia." (PMID 41510452, 2025).